HGF (hepatocyte growth factor)
Diseases named in the same sentence as HGF in open-access papers (continued):
Sharing a sentence is not in itself a finding about the gene and the disease.
myopia (continued). "Taken together, HGF is probably involved in development of the posterior eye segment, and consequently in spherical error and axial myopia." (PMID 22509107, 2012). "In the current study we investigated the association of three myopia-associated genes, GJD2, IGF1, and HGF, and their interaction with eye biometric parameters in two Chinese cohorts." (PMID 22509107, 2012). "This is supported by the fact that we and others have found the HGF gene, which codes for the primary ligand for MET, to be associated with both high and low/moderate myopia." (PMID 20011629, 2009). "Hepatocyte growth factor (HGF) and hepatocyte growth factor receptor (C-MET) genes have previously been reported to be associated with myopia in Asian family-based and case-control association studies, respectively." (PMID 19471602, 2009). "The present study examined the associative involvement of the HGF and C-MET with mild to moderate, high, and extreme high myopia phenotypes using a large Caucasian family-based cohort biased toward high myopia." (PMID 19471602, 2009). "Similarly, in a pilot study (n = 41), we demonstrated the concurrence of human myopia, oxidative stress, and hepatocyte growth factor (HGF), together with vascular endothelial growth factor (VEGF)." (PMID 41438149, 2025). "The myopia patients showed an increased tendency for higher aqueous humor HGF levels." (PMID 32477165, 2020). "The vitreal CTGF level is elevated in highly myopic eyes and may be related to the pathogenesis of high myopia, whereas increased expression of HGF may be involved in the development of idiopathic epiretinal membrane." (PMID 30665391, 2019). "Therefore, we investigated the changes in CTGF and HGF levels in the vitreous of patients with high myopia." (PMID 30665391, 2019). "None of the other HGF SNPs were observed to have statistically significant association with extreme high myopia compared to emmetropia by APL or PDT analyses." (PMID 19471602, 2009). "In addition to these significant analytical results, HGF is an excellent biological candidate gene for myopia as it potentially plays a role in the scleral remodeling process." (PMID 19471602, 2009). "The hepatocyte growth factor (HGF) gene represents a strong biological candidate for myopia." (PMID 20011629, 2009). "For example, HGF gene polymorphisms investigations reported that rs3735520 is associated with mild and moderate myopia, but not with high myopia, while rs2286194 could be related to high myopia." (PMID 31781378, 2019). "Hence, to date, HGF represents one of the strongest candidate genes for myopia." (PMID 20011629, 2009). "HGF may be a potential myopia candidate gene for further investigation." (PMID 19471602, 2009). "This analysis indicated that INFG, TNF, IL1B, EGF, HGF and OSM would be predicted to stimulate recovery from induced myopia (activators)." (PMID 38390290, 2023). "Some previous scientific evidence relates myopia to oxidative stress and myopia with growth factors, VEGF and HGF separately." (PMID 32477165, 2020). "Secondly, our data further pointed to a substantial role of interaction between these genes such as HGF and GJD, in genetic studies of myopia endophenotypes." (PMID 22509107, 2012). "HGF and C-MET are two myopia candidate genes studied in Asian populations (; personal communication, Khor C.C., Agency for Science, Technology, and Research, Singapore; December, 2007)." (PMID 19471602, 2009). "Previous works have suggested that HGF and VEGF might play a relevant role in the physiopathological molecular mechanisms present in myopia disease." (PMID 32477165, 2020). "The vitreal HGF level was not significantly different between the high myopia and VMID groups, but was significantly higher in group D than in group C in the subgroup analysis." (PMID 30665391, 2019).
myopia (continued). "Hepatocyte growth factor (HGF) and its receptor, C-MET, modulate MMP and TIMP pathways and therefore may play an active role in scleral remodeling, axial elongation, and myopia development." (PMID 19471602, 2009). "Hence, to date, PAX6, HGF, and UMODL1 remain the strongest candidates for high grade myopia and collagen, type 2, alpha 1 (COL2A1) for common myopia." (PMID 19365569, 2009). "Additionally, growth differentiation factor 15 (GDF-15), hepatocyte growth factor (HGF), and platelet-derived growth factor (PDGF)-AA were also significantly elevated in the aqueous humor in high myopia patients, indicating novel biomarkers for myopia progression." (PMID 41191163, 2025). "The strong biological role of HGF in the development of myopia makes it not unreasonable to hypothesize that other genes in the HGF signaling cascade, such as MET, may also play a critical role in myopia." (PMID 20011629, 2009). "This represents the first analysis of HGF and C-MET polymorphisms and myopia in a non-Asian cohort." (PMID 19471602, 2009). "APL testing for the HGF SNP, rs2286194, yielded a p-value that did not meet a significant level (p=0.0396 for SPH and 0.0613 for SE) when comparing the high myopia with emmetropia groups." (PMID 19471602, 2009).
acute kidney injury (15 papers, 2012 to 2025). Sudden and sustained deterioration of the kidney function characterized by decreased glomerular filtration rate, increased serum creatinine or oliguria. "Prior studies have revealed that HGF is a potent anti-inflammatory factor, whose overexpression significantly protects the kidneys from ischemia-induced acute renal failure." (PMID 38916398, 2024). "Plasmid-based vector treatments have confirmed the renotherapeutic potential of HGF as it mediated tissue regeneration and protected tubular epithelial cells from injury and apoptosis during acute renal failure." (PMID 36846323, 2023). "In preclinical animal models for acute kidney injury, systemic administration of recombinant HGF suppressed tubular cell apoptosis and renal dysfunction, and promoted regenerative cell proliferation." (PMID 28548072, 2014). "Additionally, acute renal failure is accompanied by a significant increase in the levels of medium- and macromolecular substances such as hepatocyte growth factor, tumor necrosis factor, insulin-like growth factor and epithelial cell growth factor." (PMID 36694734, 2023). "Injections of HGF stimulate kidney and liver regeneration, and prevent the onset of renal failure." (PMID 27406064, 2016). "HGF protein may be applicable to the treatment of patients with acute hepatitis or acute kidney injury." (PMID 28548072, 2014). "This enhanced effect is attributed to IronQ-induced secretion of hepatocyte growth factor (HGF) by MSCs, which activates the HGF/c-Met signaling pathway, improving MSCs' ability to treat acute kidney injury (AKI)." (PMID 41282543, 2025). "Moreover, growth factors like HGF or IGF-1 showed therapeutic potential in animal models of acute kidney injury through multiple actions that may concur to create a pro-regenerative environment." (PMID 25811887, 2015). "During acute kidney injury (AKI), tubular cell dedifferentiation initiates cell regeneration; hepatocyte growth factor (HGF) is involved in modulating cell dedifferentiation." (PMID 25793303, 2015). "Several studies have reported that serum HGF is associated with increased mortality in patients with CKD16, but the role of soluble cMet levels in predicting renal failure has not been studied in detail." (PMID 30143691, 2018).
brain tumor (15 papers, 2008 to 2025). "Hepatocyte growth factor (HGF), also called scatter factor, along with its receptor tyrosine kinase c-Met, are key determinants of brain tumor growth and angiogenesis." (PMID 39201395, 2024). "Studies of HGF/c-MET distribution in human primary brain tumors showed that expression was not limited to glial cancer cells, but was also found in supporting tumor microvasculature." (PMID 36034555, 2022). "This research also showed significantly elevated levels of HGF in the patients with brain tumors, both before and after the surgery, compared to the control group of healthy volunteers." (PMID 32607415, 2020). "This is consistent with the results of this study where preoperative HGF plasma level in patients with brain tumors was also higher." (PMID 32607415, 2020). "The following sections will first give an overview of malignant brain tumors (Section 2) and then discuss HGF/MET signaling in this specific dysregulated context (Section 3)." (PMID 33066121, 2020). "In brain tumor, Hepatocyte growth factor (HGF) and platelet-derived growth factor (PDGF), two growth factors secreted by tumor cells, appear critical to drive EndMT." (PMID 32923440, 2020). "For brain tumors, in particular, HGF/MET induces endothelial cell proliferation and migration, expression of vascular endothelial growth factor (VEGF), and tubule formation." (PMID 33066121, 2020). "It was found that preoperative plasma levels of the HGF in brain tumor patients were higher (Me = 543.16 pg/ml) than the levels found in healthy subjects (Me = 361.04 pg/ml)." (PMID 32607415, 2020). "Brain tumours secrete scatter factor (SF)/hepatocyte growth factor (HGF), the activating ligand for HGFR/MET, which has been associated with poor prognosis for GBM patients." (PMID 31616641, 2019). "Scatter factor (SF)/hepatocyte growth factor (HGF) is the activating ligand for HGFR/c-MET that have been shown to be secreted by brain tumor cells." (PMID 29263927, 2017). "The multifunctional growth factor scatter factor/hepatocyte growth factor (SF/HGF) and its receptor, c-Met, are important mediators of brain tumor growth and angiogenesis." (PMID 24294521, 2013). "The progression and recurrence of malignant brain tumors is associated with the expression of pro-angiogenic growth factors, such as VEGF and SF/HGF." (PMID 18302779, 2008). "There are many similarities between HGF/MET signaling in the different malignant brain tumors." (PMID 33066121, 2020). "However, besides VEGF, cytokines and scatter factor or hepatocyte growth factor are also secreted by astrocytoma and other brain tumors." (PMID 25866775, 2015). "Overexpression of HGF and/or MET in brain-tumor-derived cells enhances their tumorigenicity and growth, and inhibition of HGF or Met in experimental tumor xenografts suppresses tumor growth and angiogenesis." (PMID 36672409, 2023). "When dysregulated, HGF/MET signaling promotes tumor progression and angiogenesis in many cancers including brain tumors." (PMID 33066121, 2020). "Section 4 will focus on HGF/MET in specific types of primary and brain tumors and brain metastases." (PMID 33066121, 2020). "In addition, immunofluorescence staining experiments have shown HGF/MET to localize more to regions of endothelial cells in the perivascular and vascular areas of higher grade brain tumors." (PMID 33066121, 2020). "Therefore, we speculate that the mouse‐derived HGF stimulated the growth of NUGC4 cells, and that crizotinib inhibited the progression of peritoneal carcinomatosis and brain tumors in vivo." (PMID 29125233, 2017). "In contrast to the previous studies which suggest that the dysregulation of HGF/c-Met pathway may affect TRAIL-sensitivity via upregulation of DR5 level, we found that both the levels of DR4 and DR5 protein were unaltered after knocking down c-Met in TRAIL-resistant brain tumor cells." (PMID 24748276, 2014).
cyst (15 papers, 2007 to 2025). A sac-like closed membranous structure that may be empty or contain fluid or amorphous material. "The hepatocyte growth factor (HGF)-c-Met signaling axis is also implicated in cyst formation and its progression to RCC within the ESKD setting." (PMID 41301732, 2025). "Together, these findings demonstrate RhoA rescues responsiveness of CDH3-/- cysts to HGF, enabling cyst protrusion formation, correlating to cyst morphology and matrix deformation rates similar to WT cysts." (PMID 41424915, 2025). "Specifically, we calculatedthe curvature (a measure of how much a curve deviates from a straightline) ratio of the top and bottom half of each cyst, with the tophalf exposed to the larger concentration of HGF." (PMID 39007451, 2024). "Aspect ratio,a measure of cyst elongation, was significantly larger for cysts culturedin an HGF gradient compared to bath conditions in the aligned devicesbut not in the random devices." (PMID 39007451, 2024). "HGF treatment immediately promoted cell growth and proliferation (as indicated by increased cyst diameter and a high ratio of Ki67-positive cells) and morphological changes with some cysts exhibiting extended cell protrusions." (PMID 33574034, 2021). "MDCK cells in 3-D culture undergo a series of morphological changes and form polarized and growth-arrested cyst structures with hollow lumen, which re-differentiates into normal tubules upon induction by hepatocyte growth factor (HGF)." (PMID 24386484, 2013). "We showed that when cultured in a 3-D collagen gel, MDCK cells formed a polarized cyst structure, which then formed tubular networks upon stimulation with HGF, which is consistent with our published studies." (PMID 24386484, 2013). "Identifying the role of HGF in TGF-β1-treated ADPKD cyst-lining epithelial cells and their possible modulation by rosiglitazone deserves further study." (PMID 22174924, 2011). "To further examine the mechanism by which cyst formation occurs by means of p21 attenuation, we utilized the growth factor HGF." (PMID 17714589, 2007). "MDCK cells spontaneously form cysts when cultured in 3D collagen gels and undergo in vitro tubulogenesis when treated with HGF; thus HGF is functions as a molecular "switch" from tubule formation to cyst." (PMID 17714589, 2007). "MDCK cells spontaneously form cysts when cultured in 3D collagen gels and undergo in vitro tubulogenesis when treated with HGF; thus HGF functions as a "molecular switch" from cyst to tubule formation." (PMID 17714589, 2007). "For all studies, we analyzed cyst phenotypeafter 8 and 24 h of HGF gradient exposure." (PMID 39007451, 2024). "Thus it would be paradoxical that inhibition of c-MET by crizotinib would drive cyst formation unless an unidentified feedback mechanism increased levels of HGF to drive cyst formation via another target." (PMID 28209203, 2017). "However, past studies have primarily focused on the role of signaling molecules, such as HGF and cAMP on cyst and tubule structure development." (PMID 22963260, 2012). "Thus, p21 is downstream of HGF and may mediate its function in maintaining the tubular (and hence non-cystic) phenotype, such that its absence contributes to cyst formation." (PMID 17714589, 2007). "In our study, the cyst formation media contained 4 soluble factors and 2 signal inhibitors such as EGF, HGF, Wnt3a, R-spondin-1, ROCK inhibitor Y-27632, and TGF-β inhibitor A-8301." (PMID 27335264, 2016). "Another example is free floating cyst culture of MDCK cells, in which the epithelial sheet autonomously deform to form tubular protrusions upon HGF application." (PMID 23300850, 2012). "To explore this possibility further, we analyzed the effect of DDR1 inhibition on cyst formation by MDCK cells in 3D collagen matrices in the absence of HGF." (PMID 30760555, 2019).
chronic kidney disease (14 papers, 2006 to 2025). Impairment of the renal function secondary to chronic kidney damage persisting for three or more months. "During the development of chronic kidney disease or fibrosis, the expression of HGF reaches lower level than normal." (PMID 38724923, 2024). "In a mouse model of chronic renal disease, exogenous HGF administration prevented renal dysfunction and chronic mesangial damage and had therapeutic benefits for end-stage renal disease." (PMID 39457546, 2024). "The exogenous administration of HGF in different animal models of fibrosis leads to less prominent or abolishes organ fibrosis in chronic kidney disease, unilateral ureteral obstruction, and diabetic nephropathy." (PMID 34639117, 2021). "Taken together, these data suggest that IL-15 reduction, as observed for the antifibrotic factors, such as BMP-7 and HGF, may be a critical event in renal fibrogenesis and in acute and chronic kidney diseases." (PMID 34769128, 2021). "Next, we used immunofluorescence staining with a phosphorylation-specific cMet Ab to investigate whether the HGF/Met pathway is involved in kidney fibrosis in patients with IgA nephropathy (IgAN), which is one of most common chronic kidney diseases." (PMID 31530851, 2019). "Beyond its evident role in antagonizing TGF-β1 and its antifibrotic activity, the anti-inflammatory potential of HGF may also contribute to the final effects in vivo and in vitro, as renal inflammation directly contributes to progression of chronic kidney disease." (PMID 34639117, 2021). "Moreover, powerful therapeutic effects of hepatocyte growth factor (HGF)—secreting mesothelial cell sheets and BMSCs sheets were reported in a rat model of chronic kidney disease(CKD)." (PMID 37106373, 2023). "In chronic kidney disease, plasma His concentrations are inversely correlated with CRP and hepatocyte growth factor, markers that reflect inflammation." (PMID 22303484, 2012).
endothelial dysfunction (14 papers, 2011 to 2025). In vascular diseases, endothelial dysfunction is a systemic pathological state of the endothelium (the inner lining of blood vessels) and can be broadly defined as an imbalance between vasodilating and vasoconstricting substances produced by (or acting on) the endothelium. "Hypothetically, serum HGF is increased in hypertensive individuals to prevent endothelial dysfunction." (PMID 39457546, 2024). "In hypertensive individuals, serum HGF secretion increases in response to high BP to prevent endothelial dysfunction." (PMID 39457546, 2024). "We have investigated the role and importance of sulfation pattern, location, regioisomers, and spatial orientation of distal sulfate groups on the modulation of endothelial dysfunction through their interaction with hepatocyte growth factor (HGF)." (PMID 34124676, 2021). "However, concentrations of tissue factors like IGFBP-1, uPA, and HGF were comparable to UE, suggesting less endothelial dysfunction in Sub2." (PMID 34893580, 2021). "HGF may be upregulated in response to elevated blood pressure to counter endothelial dysfunction." (PMID 25047123, 2014). "Key proteins, elevated in severe cases, including SYND1, S100A12, HGF and CDCP1, reflect processes such as endothelial dysfunction, neutrophil activation, tissue remodeling and systemic inflammation." (PMID 40429886, 2025). "These revealed that HGF could promote quick reestablishment of adherent junction VE-cadherin and decrease endothelial paracellular and transcellular permeability during LSP-induced endothelial dysfunction with the involvement of mTORC2 (rictor) and mTORC1 (raptor) pathways." (PMID 34707661, 2021).